AKT1 (AKT serine/threonine kinase 1)
Diseases named in the same sentence as AKT1 in open-access papers (continued):
Sharing a sentence is not in itself a finding about the gene and the disease.
tumor (continued). "The localization of AKT1 and ESR1 in tumor cells, alongside SRC and IL6 in myeloid cells, highlights potential mechanisms through which the decoction impacts tumor-immune interactions, potentially altering immune surveillance and tumor progression in high-risk locally advanced NPC." (PMID 40746726, 2025). "Additionally, miR-99a acts as a tumor suppressor in NSCLC by inhibiting cell migration and invasion through AKT1 downregulation." (PMID 40167762, 2025). "The top five genes with the highest degree values are AKT1, SRC, EGFR, BCL2, and CASP3, suggesting that FOA may exert its anti-tumor effects by acting on multiple targets." (PMID 41050420, 2025). "Genetic analysis identified an AKT1 E17K mutation, characteristic of PSP, and absence of programmed cell death ligand 1 (PD-L1) expression in the tumor." (PMID 39758787, 2025). "In LAPC4-CR-bearing mice, a single application of Compound 4 effectively suppressed the AKT1 signaling pathway and tumor growth without significantly affecting blood glucose levels." (PMID 40478506, 2025). "Further mechanism studies showed that LRRC1 enhances PDK1 stability by promoting its deubiquitination via USP7, thereby increasing AKT1 phosphorylation levels and activating the AKT/GSK3β/β-catenin/VEGFA signaling pathway, ultimately accelerating tumor angiogenesis in HCC." (PMID 41369408, 2025). "The AKT1, 2 and 3 isoforms appear to have differential, non-redundant and opposing effects on tumor cell and fibroblast motility, although, collectively, AKT exerts significant effects on the development of the peritumor stroma." (PMID 38786020, 2024). "As a crucial protein regulating aerobic glycolysis in tumor cells, the activation of AKT1 can increase GLUT expression and maintain the activity of hexokinase and phosphofructokinase 2 during glycolysis, resulting in tumor cells utilizing more glucose for aerobic glycolysis." (PMID 39769177, 2024). "The results indicated that AKT1 and MAPK1 were present in different tumor stages." (PMID 38835342, 2024). "The observed effects of Rapamycin on tumor suppression are likely to involve the autophagy process, evidenced by the inhibition of autophagy modulators (TGFβ1, RGS19 and AKT1), autophagosome biogenesis components (AMBRA1, ATG9B and TMEM74) and autophagy byproducts (APP)." (PMID 38276004, 2024). "Therefore, when tumor cells resist apoptosis signals by upregulating BCL2L11, AKT1, and LMNA genes, they simultaneously exhibit reduced responsiveness to lipid receptor activity." (PMID 39381047, 2024). "However, capivasertib can deliver monotherapy and combination activity beyond tumours with alterations in PTEN, PIK3CA or AKT1." (PMID 39284898, 2024). "Overexpression of AKT1 and AKT2 are frequent events in BC that enhance tumor cell survival." (PMID 39796647, 2024). "Tumor-derived exosomal circPSMA1 facilitated the metastasis in triple-negative breast cancer through the regulation of miR-637/Akt1/β-catenin regulatory axis." (PMID 37525158, 2023). "From the results, we noticed that tumor cells highly expressed AUP1 significantly correlated with proliferation marker (MCM2, MCM6), PI3K-AKT-MTOR pathway (Akt1, TSC1, mTOR, Foxo1), and autophagy signaling (Atg3, Atg4B, Atg4D, Atg7, Atg9A, Atg16L1) in IDH wildtype tumor cells." (PMID 37029364, 2023). "In addition, it was known that the phosphorylation of Akt1 and STAT3 regulates the transcription of HIF-1α, a core molecule that induces tumor angiogenesis." (PMID 36647454, 2023). "Not all tumor cells depend on KRAS G12C for survival, as other alternative mutations, such as those involving AKT1, AKT2, PI3KCA, and PTEN, can activate the PI3K–AKT pathway." (PMID 37894382, 2023). "In addition, the organoids recapitulated the genetic alterations of the patient’s primary tumor (e.g., single nucleotide variations in BMP4, cadherin related 23 (CDH23), AKT serine/threonine kinase 1 (AKT1)), as uncovered by whole-exome sequencing." (PMID 37614709, 2023).
tumor (continued). "Mutations in genes such as PIK3CA, phosphatase and tension homologues (PTEN), AKT1, and tuberous sclerosis 1/2 (TSC1/2) can all lead to dysregulation of signalling pathways, which can drive important physiological processes such as tumour metabolism, proliferation, angiogenesis, and metastasis." (PMID 37489050, 2023). "The triple-drug combination significantly (p < 0.0001) reduced the gene expression levels of VEGF, VEGFR, PI3K, PDK1, AKT1, mTOR and GSK3β while it significantly (p < 0.0001) enhanced the expression of PTEN, when compared with the tumor-control (TC) and other treatment groups." (PMID 37025487, 2023). "When comparing the untreated MAS98.12 and HbCx39 models, we found that Akt‐pS473, Akt‐pT308, Akt1‐pS473, and Akt2‐pS474 all had an increased expression in MAS98.12, which may explain the effect of LXR activation on tumor growth observed in this model." (PMID 37341140, 2023). "The tumor phospho‐Akt1/2/3 levels are also not significantly different between Duke’s stage A/B and C/D tumors (unpaired two‐tailed t‐test)." (PMID 34919787, 2022). "Moreover capivasertib has also demonstrated single-agent clinical activity in patients with BC harbouring AKT1 and PIK3CA mutant tumours and germ-line PTEN alterations." (PMID 36241868, 2022). "Taken together, this study reported a new regulatory axis linc00958/miR-185-5p/RSF-1 in cisplatin resistance and tube formation in CC via AKT1/GSK3β/VEGFA pathway and knockdown of linc00958 could also inhibit the tumor growth and angiogenesis." (PMID 36056431, 2022). "Among these survival-related genes, 33 genes had higher expression in tumor tissues than in normal tissues like EGFR, AKT1, and HSP family genes, suggesting they could serve as diagnostic markers to distinguish normal from tumoral samples." (PMID 35873484, 2022). "Our preliminary data show that a combination of a natural compound (homoharringtonine) and an AKT1 inhibitor (A674563) that is important for N-Myc protein stability significantly reduces the expression of INSM1, N-Myc, and NB tumor cell growth (unpublished results)." (PMID 36290282, 2022). "Moreover, in the phase I study, M2698 was shown to strongly inhibit AKT1, AKT3, and p70S6K in the tumor tissue." (PMID 35525984, 2022). "In the expanded testing panel that used advances in genetic testing assays, PIK3CA, AKT1 and PTEN alterations were identified in tumours from 76 (54%) of the 140 participants in the intention-to-treat population (39 who received capivasertib and 37 who received placebo)." (PMID 35671774, 2022). "Allograft tumor cells were subcutaneously injected into nude mice, which were then injected intraperitoneally with PBS or 5-HT three times a week to analyze the effect of 5-HT on tumor development after Akt1 knockout." (PMID 35664068, 2022). "Thus, the addition of the AKT inhibitor capivasertib resulted in significantly longer PFS, and the benefit was more pronounced in patients with PIK3CA/AKT1/PTEN-altered tumours." (PMID 35954393, 2022). "These experiments suggest that tumor tissues with high KRAS expression are responsive to niraparib and that the enrichment of AKT1 during treatment might lead to drug resistance." (PMID 36230574, 2022). "At the same time, AKT1 downregulation increased CD3+ cells and T-cell density in tumor tissues." (PMID 33794833, 2021). "Consistently, ectopic expression of the myristoylated form of AKT1 (myr-AKT1) significantly repressed USP12 expression in both human and mouse tumour cells; knockdown of endogenous AKT1 or AKT2, the two major isoforms of AKT, induced higher levels of USP12 than did the control treatment." (PMID 34381028, 2021).
tumor (continued). "Furthermore, a novel dual PI3K/mTOR inhibitor, VDC-597, showed dose-dependent inhibition of both Akt1 and 4eBP1, reduction of proliferation, migration and VEGF production, and promotion of tumor cell apoptosis in three canine HSA cell lines." (PMID 34296746, 2021). "Because the majority of non-NF-2 meningioma driver mutations such as SMO, AKT1, SMARCB1, and TRAF7 normally occur mutually exclusive of NF-2, the expected rate of these mutations would be lower in high-grade tumor cohorts." (PMID 34638590, 2021). "However, though more than 40 PSP cases have been reported with AKT1 E17K mutation, malignant progression has been rarely reported, which indicated that single E17K mutation on the PH domain of the AKT1 gene might not be sufficient to initiate the malignant transformation of the tumor." (PMID 34568352, 2021). "While expression of Smao1-EGFP alone did not result in tumour formation, co-expression of constitutively active human AKT1, lead to ocular melanomas presenting in the retina, among other tumour types, suggesting a role for Smao1 in zebrafish tumorigenesis." (PMID 34149931, 2021). "Yiqi formula inhibited the TNBC xenograft tumor growth by reducing p-EGFR and p-AKT1." (PMID 34225726, 2021). "As aPKC and AKT1 are both overexpressed in BCC and are required for tumor growth, our results suggest that BCCs activate both kinases downstream of PI3K to promote cell cycle progression and continued tumor growth." (PMID 34268113, 2021). "The high expression of Akt2 correlated with the histopathological differentiation, portal invasion, and the number of tumor nodules, while Akt1 did not correlate with any of these clinicopathological features." (PMID 33670268, 2021). "In both tumor models, 17-DMAG inhibited not only AKT1 and ERK phosphorylation but also proliferative markers such as CyclinD1 and induced cleaved Caspase3 expression, indicating a similar effect on HSP90 regulation of the AKT1/ERK pathway in vitro." (PMID 35095481, 2021). "Both the British and Indian tumor histology patterns revealed higher expression of AKT2 while expressions of AKT1 and AKT3 were not significant when observed in both liver and lung metastasized FPPE samples." (PMID 33227065, 2020). "Furthermore, in NSCLC tumor tissues and cell lines (A549 and H1299), MALAT1 can upregulate VIM and downregulate CDH1 and is involved in the phosphorylation of AKT1, RPS6KB1, and MTOR." (PMID 32438606, 2020). "In this present study, we found that depletion of Akt2 or Akt3 did not alter the tumor development or local invasion while we confirmed our prior data with the Akt1 knock out model." (PMID 33110146, 2020). "Besides, in NSCLC tumor tissues and cell lines (A549, H1299, H1975, HCC827), GAS5 can deregulate the expression of phospho-EGFR, phospho-MAPK1, phospho-AKT1, and IGF1R." (PMID 32438606, 2020). "In addition, copy number gain of PIK3CA was present in all samples, as well of AKT1 in TC1 and TC4 PDX tumours." (PMID 33144587, 2020). "In the mean while, to further explore the possible mechanism of anti-AEG-1 ScFv on tumor growth inhibition in vivo, we also detected intracellular expression changes of AEG-1, Akt1,c-Myc, NF-ƘB and cleaved Caspase 3 as well as tumor cell apoptosis in Ad-sta-SFv treated tumor tissues." (PMID 32190003, 2020). "By day 21 there was a difference in mouse weight between the six groups (NC-control, NC-JSD, si-AKT1-control, si-AKT1-JSD, oe-AKT1-control, oe-AKT1-JSD) and by day 28, oe-AKT1-control mice had the heaviest weight due to ascites, large tumor load, and metastatic weight." (PMID 31772677, 2019). "To verify whether circNRIP1 plays a tumour promotor role via the AKT/mTOR pathway by sponging miR-149-5p, we attempted to detect the expression level of AKT1, the target of miR-149-5p, in GC cells." (PMID 30717751, 2019). "In conclusion, our study suggests that AKT1, PRDM10, and FASN may be tumour promoters and that FLNA may be a tumour suppressor in PCa." (PMID 30872976, 2019).
tumor (continued). "The expression levels of p-AKT1, p-mTOR, PFK and LC3 were observed in PDX tumours." (PMID 30717751, 2019). "BAY 1125976 was well tolerated and inhibited AKT1/2 signaling but did not lead to radiologic or clinical tumor responses." (PMID 31835495, 2019). "Third, VEGF‐induced corneal and tumor angiogenesis were significantly attenuated in mice lacking Akt1." (PMID 30984553, 2019). "AKT1-MMTV mice do not show sustained dysplasia or neoplasia in the mammary gland, proposing AKT1 has no transforming ability." (PMID 31752925, 2019). "In the present study, we investigated the role of Akt1 in angiogenesis and focused on EC functions, as well as retinal, corneal and tumor angiogenesis, in mice lacking Akt1." (PMID 30984553, 2019). "Importantly, interrupting the TRIB3/AKT1 interaction by a modified α-helix peptide, Pep2–Ae, accelerated FOXO1 degradation, reduced SOX2 accumulation, and decreased the tumor-initiating capacity in MMTV-PyMT and PDX mice." (PMID 31844113, 2019). "The cliques involving AKT1 (METH), PTEN (mRNA) and AKT1 (METH), PIK3R2 (mRNA) can be construed as tumor suppressing, while cliques involving AKT1 (METH), CCND1 (mRNA) and AKT1 (METH), GRB2 (CN) probably are tumor activating." (PMID 30059495, 2018). "Ablation of Akt1 in the TME generated an inhibitory effect on tumor size, without significant change in animal survival, while elimination of Akt2 or Akt3 resulted in increased tumor size, metastasis, and decreased survival time." (PMID 28929459, 2018). "We are first to report that in PTSMTs, a non-canonical activation of WNT, independent of beta-catenin, drives tumor cell proliferation via MTOR/AKT1, MYC and Cyclin D2." (PMID 29881541, 2018). "AKT1 and AKT2 genes enhance tumor growth by promoting epithelial-to-mesenchymal transition (EMT) through PI3K activation, and the tumor suppressor gene of the PTEN antagonist PI3K/AKT pathway induces AKT-regulated tumor metastasis through loss-of-function mutations." (PMID 28961226, 2017). "Two of these patients (patients 037 and 045) had an APC variant detected in the primary tumour but not in the PM sample whilst for the third patient (patient 051) PIK3CA, AKT1 and SMAD4 mutations were detected in the primary tumour but not in the PM sample." (PMID 29029407, 2017). "Similar and even more striking effects were observed on several tyrosine kinase families including molecules known to be relevant to the proliferation, survival and invasion mechanisms of tumor cells like p38α, ERK1/2 and JNK1/2/3, Akt1/2/3 and TOR, Src and Lyn, STATs as well as βCatenin." (PMID 28186982, 2017). "Importantly, induction of AKT1 knockdown slowed xenograft tumour growth, whereas AKT2 knockdown resulted in a striking regression of tumour size suggesting decreased tumour survival capacity." (PMID 28082369, 2017). "Moreover, Akt1-KD as well as the inhibition of HR proteins such as BRCA1 is known to induce autophagy and subsequently, increase tumor cell survival." (PMID 29156644, 2017). "There are likely a number of reasons why AKT1(E17K) does not phenocopy artificially-activated AKT1 with respect to HER2-mediated tumor progression." (PMID 27004402, 2016). "A recent paper reported levels of Akt3 similar to Akt1 and2 in lung tumors, but found that ablating Akt3 did not change tumor growth compared to controls." (PMID 27533079, 2016). "In SKP2/N-RasV12 and SKP2/myr-AKT1 mice, the molecular substrates of SKP2 in mediating its oncogenic activity presumably differ from the canonical targets of SKP2 previously identified in many tumor types." (PMID 25537506, 2015). "Tumor development was detected in myr-AKT1 mice only 28 weeks after hydrodynamic gene delivery (not shown), in accordance with previous data." (PMID 25537506, 2015).
tumor (continued). "Similar to Akt1, SGK1 is highly expressed in a wide variety of tumor cells." (PMID 25015419, 2014). "Furthermore, AKT1 stimulated CA916798 expression through mTOR pathway in both A549 and A549/CDDP cell lines, which was also observed in the xenografted tumor in nude mice." (PMID 23667466, 2013). "Ablation of Akt1 or Akt2 significantly delayed tumor onset and tumor growth rate but did not significantly alter lung metastasis." (PMID 23919516, 2013). "Additionally, HA-tagged Akt1 was overexpressed in DU145, and tumor growth in subcutaneous and intra-tibia bone metastasis models were analyzed." (PMID 23902739, 2013). "Therefore, the myrAkt1 cannot be inhibited by PTEN, a tumor suppressor that acts as a negative regulator of the PI3K pathway, and will constitutively activate the Akt1 downstream signals." (PMID 22623957, 2012). "Seventeen tumours (23.0%) were negative on Akt1 staining, 46 (62.1%) were Akt1 weak positive and 9 (12.2%) were strong positive, results for two tumours were not interpretable." (PMID 22842582, 2012). "BT474 tumours excised were lysed and protein extracts were analysed by western blotting to detect tyrosine phosphorylated ErbB-2 (PY1248), total ErbB-2, phosphorylated ERK1/2, total ERK1/2, phosphorylated AKT1 and total AKT1 proteins." (PMID 21847123, 2011). "In fact, even when we expressed the constitutively active human AKT1 driven by a strong ubiquitous β-actin promoter, no tumor was found in more than 50 fish over an 18 months period." (PMID 19555497, 2009). "Both groups used activated ErbB2 models of tumourigenesis in Akt1-/- and Akt+/+ backgrounds and demonstrated the importance of Akt1 in mediating ErbB2-induced tumourigenesis: mice lacking Akt1 either failed to develop tumours or tumourigenesis was delayed." (PMID 18700973, 2008). "Expression of activated Akt1 in the MMTV-c-ErbB2 model did not induce more differentiated glandular tumours, but rather accelerated tumour formation often appearing to cause necrosis." (PMID 18700973, 2008). "The downregulation of p-PI3K and p-AKT confirms suppression of survival signaling, while the inhibition of key oncogenic regulators AKT1, MTOR, HIF1A, SRC, and ESR1 suggests broader effects on tumor metabolism, hypoxia adaptation, and growth factor receptor pathways." (PMID 40746726, 2025). "Given the absence of a selective AKT1(E17K) inhibitor, it remains unclear whether blocking the endogenous mutant AKT1 alone is sufficient to inhibit tumor growth." (PMID 40478506, 2025). "However, in the HCC mouse model, Akt1-OE CTLs exhibited delayed effector function compared with Akt2-OE CTLs and failed to eliminate tumor cells initially." (PMID 40139836, 2025). "DMG single-cell RNAseq data showed PRKACA, and AKT1 were expressed preferentially in malignant cells while PAK2 was also present in the immune and oligodendrocytic populations suggesting targeting PAK2 can lead to off-tumor toxicity but PRKACA and AKT1 may be more selective targets." (PMID 39954016, 2025). "However, only Akt2-OE CTLs, not Akt1-OE CTLs, effectively eliminate tumor cells in vivo, accompanied by distinct exhaustion-related gene expression." (PMID 40139836, 2025). "Variations within genes of the MAPK signaling pathway in TECs, such as amplifications in CDC42, HSPB1, NRAS, and deletions in AKT1, MAPK1, might reveal their significance in HCC, possibly related to their roles in tumor growth and progression, particularly in signaling pathways." (PMID 39484208, 2024). "However, in R‐MCF7/R‐ZR75.1 cells, combining targeted inhibition of AKT1 (MK2206 or siAKT1) and activators of STING signaling (ADU‐S100 or HT‐DNA) significantly increased the percentage of DCs that engulfed CFSE‐labeled tumor cells much more than activators of STING signaling monotherapy." (PMID 39023171, 2024).